SLC37A4 (solute carrier family 37 member 4)
Description:
Inorganic phosphate and glucose-6-phosphate antiporter of the endoplasmic reticulum. Transports cytoplasmic glucose-6-phosphate into the lumen of the endoplasmic reticulum and translocates inorganic phosphate into the opposite direction. Responsible for glucose production through glycogenolysis and gluconeogenesis and plays a central role in homeostatic regulation of blood glucose levels.
Synonyms: TRG-19; G6PT; G6PT1; PRO0685; TRG19; GSD1b; GSD1c; GSD1d; SPX4; CDG2W; G6PT2; G6PT3
Target class: SLC37 family of phosphosugar/phosphate exchangers; Transporter; Electrochemical transporter; SLC superfamily of solute carriers
Gene: Protein-coding gene on chromosome 11 (119,023,751 to 119,030,906, reverse strand). Ensembl gene ENSG00000137700.
Subcellular location: Endoplasmic reticulum membrane
Subcellular location (Human Protein Atlas): Mitochondria
Genetic constraint (gnomAD): Loss-of-function variants: 41 observed, 42.48 expected, observed/expected ratio (o/e) 0.97, 90% interval 0.75 to 1.25. The upper end of that interval is the gene's LOEUF score, 1.25, which puts it in group 5 of 6, group 1 being the genes least tolerant of losing a copy. Missense variants: 526 observed, 534.35 expected, observed/expected ratio (o/e) 0.98, 90% interval 0.92 to 1.06. Synonymous variants: 215 observed, 205.51 expected, observed/expected ratio (o/e) 1.05, 90% interval 0.94 to 1.17.
Homologues: Orthologues: chimpanzee SLC37A4 (99% identical), macaque SLC37A4 (98% identical), dog SLC37A4 (97% identical), pig SLC37A4 (95% identical), rabbit SLC37A4 (95% identical), guinea pig SLC37A4 (93% identical), mouse Slc37a4 (93% identical), rat Slc37a4 (85% identical), tropical clawed frog slc37a4 (80% identical), zebrafish slc37a4a (74% identical), Caenorhabditis elegans slc-17.2 (21% identical), Caenorhabditis elegans eat-4 (20% identical), and 43 more. Paralogues in human: SLC17A6 (21% identical), SLC17A8 (21% identical), SLC37A1 (21% identical), SLC17A7 (21% identical), SLC17A1 (19% identical), SLC17A5 (19% identical), SLC17A4 (19% identical), SLC37A2 (19% identical), SLC17A2 (18% identical), SLC17A9 (17% identical), SLC37A3 (16% identical), SLC17A3 (16% identical).
Diseases named in the same sentence as SLC37A4 in open-access papers:
SLC37A4 is named in the same sentence as 69 diseases in open-access papers, as found by Europe PMC text mining. Sharing a sentence is not in itself a finding about the gene and the disease. The quoted sentences say what the papers report.
Glycogen storage disease type Ib (22 papers, 2008 to 2025). "Glycogen storage disease type Ib is caused by a mutation in the SLC37A4 gene, resulting in a deficiency of the glucose-6-phosphate transporter." (PMID 40428338, 2025). "Glycogen storage disease type Ib (GSD Ib) is a rare disorder characterized by impaired glucose homeostasis caused by mutations in the SLC37A4 gene." (PMID 38605407, 2024). "Glycogen storage disease type Ib (GSD-Ib) is a rare inborn error of glycogen metabolism caused by mutations in SLC37A4." (PMID 38622211, 2024). "Deficiency of glucose-6-phosphate translocase (G6PT/SLC37A4) leads to glycogen storage disease type Iβ (GSD-1β)." (PMID 35251008, 2022). "A molecular diagnosis of glycogen storage disease Ib caused by compound heterozygous mutations (p.G149E and p.G149E) in the SLC37A4 gene (OMIM: 602671) was detected by rapid CES." (PMID 34490048, 2021). "Glycogen storage disease type Ib (GSD Ib) is a rare disorder of glycogen metabolism due to mutations in SLC37A4 encoding the glucose-6-phosphate transporter of the endoplasmic reticulum." (PMID 32838757, 2020). "Glycogen storage disease type Ib (GSD Ib) (Orphacode 79,259) is a rare autosomal recessive disease, with an estimated prevalence of 1: 500,000, due to mutations in SLC37A4 encoding the glucose-6-phosphate transporter (G6PT) of the endoplasmic reticulum." (PMID 40416752, 2025). "Secondly, Glycogen Storage Disease Ib (GSDIb, OMIM#232220) is due to autosomal recessive mutations in SLC37A4 which encodes a protein that transports glucose-6-phosphatase from the cytosol to the endoplasmic reticulum where the enzyme acts." (PMID 23171239, 2012). "Glycogen storage disease type Ib (GSDIb, OMIM#232220) is an autosomal recessive disorder caused by a defect in the glucose‐6‐phosphate transporter (G6PT1) encoded by the solute carrier family 37 members 4 (SLC37A4) gene." (PMID 38370424, 2023).
neutropenia (20 papers, 2011 to 2025). A decrease in the number of neutrophils found in the blood. "Neutropenia is a key characteristic in patients harboring mutations in patients harboring deleterious mutations in SLC37A4 leading to GSD1b." (PMID 36865166, 2023). "Interestingly, failure to eliminate a phosphorylated glucose analog led to neutropenia in patients with SLC37A4 and G6PC3 deficiency." (PMID 38034009, 2023). "A deleterious mutation in SLC37A4 gene was identified in all GSD1b patients, and all had an ANC below 1000 cells/ mm3, indicative of neutropenia." (PMID 36865166, 2023). "Slc37a4−/− mice display neutropenia and have neutrophils with impaired chemotaxis and reduced chemokine production." (PMID 32428862, 2020). "The sibling (P5–1 and P5–2) with whole SLC37A4 deletion represented both severe neutropenia and leukopenia." (PMID 32005221, 2020). "In myeloid phenotype, SLC37A4 and G6PC3 together are required to maintain neutrophil homeostasis and their deficiency leads to immune deficiency, characterized by neutropenia and neutrophil dysfunction." (PMID 32005221, 2020). "Defects in SLC37A4, glucose-6-phosphate transporter (G6PT), have been associated with glycogen storage disease 1b and 1c, characterized by recurrent infections and neutropenia due to disturbed blood glucose metabolism." (PMID 27187611, 2016). "A transmembrane protein of the Golgi apparatus is also involved in other disorders comprising neutropenia, such as glycogen storage disease Ib (SLC37A4), G6PC3 and Cohen's disease, but whose phenotypic expression also involves other systems." (PMID 21595885, 2011). "Congenital neutropenias due to mutations in ELANE, SBDS or HAX1 or in the setting of glycogen storage disease (GSD) which is caused by SLC37A4 mutation, often require prolonged granulocyte colony stimulating factor (G-CSF) therapy to prevent recurrent infections and hospital admission." (PMID 31788408, 2019).
glycogen storage disease (13 papers, 2011 to 2026). "Patients with TAZ or SLC37A4 mutations showed cardiomyopathy or glycogen storage disease as their main clinical phenotype, respectively." (PMID 35525891, 2022). "Meanwhile, the glycogen storage disease panel covering 29 genes showed a heterozygous VUS in SLC37A4, c.1176T>G (p.S392R)." (PMID 37296576, 2023). "Mutations of the genes involved in hemochromatosis, alpha 1-antitrypsin deficiency (SERPINA1), glycogen storage diseases (G6PC, SLC37A4), porphyries (HMBS, UROD), tyrosinemia (FAH), and Wilson’s Disease (ATP7B) increase the susceptibility to HCC." (PMID 36676960, 2022).
Glycogen storage disease type 1b (7 papers, 2009 to 2024). "Slc37a4 is involved in the transmembrane transport of glycerol-6-phosphate; deficiency of this enzyme in humans has been implicated as the cause of glycogen storage disease type 1b (in contrast to the more common type 1a variant which is caused by deficiency of glucose-6-phosphatase)." (PMID 19915678, 2009).
Glycogen storage disease type I (6 papers, 2014 to 2024). "Glycogen storage disease type I (GSDI) is an inborn error of carbohydrate metabolism caused by mutations of either the G6PC gene (GSDIa) or the SLC37A4 gene (GSDIb)." (PMID 32306986, 2020). "Mutations in SLC37A4 are estimated to account for about 20% of the GSD type I (or Von Gierke disease) characterized by the accumulation of glycogen in some organs and tissues." (PMID 29695245, 2018).
Hypoglycemia (5 papers, 2022 to 2025). A decreased concentration of glucose in the blood. "Our patient presented initially at the age of 2 months with severe hypoglycemia, lactic acidosis and hepatomegaly and based on family history she was found homozygous to the c.466G > A pathogenic variant in SLC37A4 gene confirming her clinical diagnosis of GSD1b." (PMID 36507137, 2022). "Patients with mutations in SLC37A4 present with several metabolic complications, particularly hepatomegaly and enlarged kidneys due to the accumulation of glycogen but also often have signs of dyslipidaemia and hypoglycemia." (PMID 36472367, 2022).
Autoimmunity (3 papers, 2014 to 2020). The occurrence of an immune reaction against the organism's own cells or tissues. "An increased autoimmunity risk for GSD-Ib patients has also been reported, moreover, SLC37A4 seems to be involved in autophagy." (PMID 29719821, 2018). "Nevertheless, the generally low prevalence of autoimmune diagnoses could also result from the CDG represented in our group which lacks (e.g., G6PC3-, SLC37A4- and GALNT3-CDG) more extensive autoimmunity reports." (PMID 32635232, 2020).
congenital neutropenia (3 papers, 2011 to 2021). "Two of these three proteins are involved in congenital neutropenia: the translocase (SLC37A4), previously named G6PT1, transports glucose 6 phosphate between the cytoplasm and the lumen of the endoplasmic reticulum, while G6PC3 is a catalytic protein." (PMID 21595885, 2011).
glioblastoma (2 papers, 2016 to 2023). The most malignant astrocytic tumor (WHO grade IV). "U87 glioblastoma monolayer cells were transiently transfected with a scrambled sequence (siScrambled, white bars) or siRNA directed against G6PC3 (siG6PC3, black bars), or SLC37A4 (siSLC37A4, black bars)." (PMID 38034009, 2023).
glioma (2 papers, 2023 to 2024). A benign or malignant brain and spinal cord tumor that arises from glial cells (astrocytes, oligodendrocytes, ependymal cells). "With regards to disease progression, our findings further suggest an association between the expression levels of SLC37A4 and the transition from low-grade glioma state to GBM, adding to their angiogenic and chemoresistance phenotype." (PMID 38034009, 2023). "Next, qPCR analysis revealed that the expression of G6PC3, SLC37A2, and SLC37A4 was considerably higher in all four glioma cell lines tested when compared to HepG2 cells." (PMID 38034009, 2023). "Higher expression in G6PC3, SLC37A2, and SLC37A4 was found in GBM tumor tissues in comparison to low-grade glioma and healthy tissue." (PMID 38034009, 2023). "The knockdown of G6PC3 and SLC37A4 in neurospheres resulted in a significant reduction in the expression levels of CSC markers, including EMT biomarkers, all collectively associated with stemness, self-renewal capacity, and invasive properties of glioma stem cells." (PMID 38034009, 2023).
hypertriglyceridemia (2 papers, 2015 to 2021). A laboratory test result indicating elevated triglyceride concentration in the blood. "Our findings identified a novel LPL gene frameshift mutation combined with SLC37A4 gene compound heterozygous mutations in a GSD Ib infant with severe hypertriglyceridemia." (PMID 34485189, 2021). "Though LPL mutation in patients with hypertriglyceridemia has been reported, a combination of an LPL gene frameshift mutation with compound heterozygous mutations of the SLC37A4 gene is rare." (PMID 34485189, 2021).
brain cancer (1 paper, 2023). A primary or metastatic malignant neoplasm affecting the brain. "In conclusion, our study highlights an original and underestimated potential of G6PC3 and SLC37A4 as prognostic markers and therapeutic targets in brain cancer." (PMID 38034009, 2023).
disorder of glycosylation (1 paper, 2021). A disease that has its basis in the disruption of glycosylation. "This causes mislocalization of the glucose‐6‐phosphate transporter to the Golgi leading to a congenital disorder of glycosylation type II (SLC37A4‐CDG)." (PMID 33728255, 2021).
Hepatic steatosis (1 paper, 2016). Steatosis is a term used to denote lipid accumulation within hepatocytes. "In the present study, apigenin also upregulated mRNA expression of hepatic Slc37a4 mRNA, whose expression was decreased during the progression of liver fibrosis, and suppression of this molecule was associated with stimulation of de novo lipogenesis and the development of hepatic steatosis." (PMID 27213439, 2016).
hepatoma (1 paper, 2023). "Consistent with our in silico data analysis, functional experiments were performed using several established GBM-derived cell lines in which high expression of G6PC3, SLC37A2, and SLC37A4 in comparison to HepG2 hepatoma cells was observed." (PMID 38034009, 2023).
Niemann-Pick disease, type C1 (1 paper, 2025). Type C Niemann-Pick disease associated with a mutation in the gene NPC1, encoding Niemann-Pick C1 protein. "This was followed by PYGL gene (GSD6, 6 patients/7 variants), NPC1 (Niemann-Pick disease type C1, 5 patients/6 variants) and SLC37A4 (GSD1b/1c, 5 patients/4 variants)." (PMID 41165782, 2025).
osteosarcoma (1 paper, 2023). A usually aggressive malignant bone-forming mesenchymal neoplasm, predominantly affecting adolescents and young adults. "These differential splicing events, such as ES in the LMO7 and SLC37A4 loci, were further defined as osteosarcoma‐specific AS events." (PMID 37457661, 2023).
renal fibrosis (1 paper, 2026). A final common manifestation of a wide variety of chronic kidney diseases characterized by glomerulosclerosis and tubulointerstitial fibrosis. "In the context of renal fibrosis phenotype ontology (RENAL_FIBROSIS), upregulation was observed in ANTXR1, MUC1, SLC37A4, and NPHP4, while ARL3 and NPHP3 were significantly downregulated." (PMID 41573374, 2026).
cancer (4 papers, 2006 to 2023). A tumor composed of atypical neoplastic, often pleomorphic cells that invade other tissues. "SLC37A4’s potential role included regulation of calcium-mediated signaling, which is known to control cancer cell proliferation, cell cycle division, extracellular matrix degradation, and response to growth factors." (PMID 38034009, 2023). "Several underestimated roles for the SLC37A4 as a potential regulator of human U87 GBM cancer cells’ invasive phenotype and of angiogenic processes were documented in brain endothelial cells." (PMID 38034009, 2023). "SLC37A4 senses and transports G6P from the cytoplasm to the ER lumen where it is hydrolyzed by the G6PC, the latter activity being linked to glycogen turnover in cancer cells." (PMID 38034009, 2023).
SLC37A4 also shares sentences with these, for which no sentence is quoted: inflammatory bowel disease (4 papers); immune deficiency (3); infection (3); lactic acidosis (3); metabolic disorder (3); bacterial infections (2); brain tumor (2); cardiomyopathy (2); genetic disease (2); hyperlipidemia (2); immunodeficiency (2); leukopenia (2); nephromegaly (2); Type II diabetes (2); adenocarcinoma (1); alpha 1-antitrypsin deficiency (1); autism (1); autoimmune disorders (1); autoimmune thyroiditis (1); breast carcinoma (1); chronic granulomatous disease (1); developmental delay (1); dilated cardiomyopathy (1); dyslipidaemia (1); glomerulopathy (1); glycogen storage disease type 1a (1); hearing loss (1); hemochromatosis (1); Hypercholesterolemia (1); Hyperglycemia (1).
A further 20 diseases each share a sentence with SLC37A4 in 1 paper.